ZNF324B (zinc finger protein 324B)
Description:
May be involved in transcriptional regulation.
Synonyms: FLJ45850
Tractability: PROTAC: UniProt records ubiquitination sites on it; ubiquitination databases record sites on it.
Gene: Protein-coding gene on chromosome 19 (58,450,369 to 58,459,868, forward strand). Ensembl gene ENSG00000249471.
Subcellular location: Nucleus
Subcellular location (Human Protein Atlas): Nucleoli; Cytosol
Pathways (Reactome):
Gene expression (Transcription): Generic Transcription Pathway
Gene Ontology:
Molecular function: DNA-binding transcription factor activity, RNA polymerase II-specific; RNA polymerase II cis-regulatory region sequence-specific DNA binding
Biological process: regulation of transcription by RNA polymerase II; regulation of DNA-templated transcription
Cellular component: nucleus
Genetic constraint (gnomAD): Loss-of-function variants: 6 observed, 9.95 expected, observed/expected ratio (o/e) 0.6, 90% interval 0.33 to 1.19. That is too few expected variants to judge how well the gene tolerates losing a copy. Missense variants: 637 observed, 774.81 expected, observed/expected ratio (o/e) 0.82, 90% interval 0.77 to 0.88. Synonymous variants: 315 observed, 322.77 expected, observed/expected ratio (o/e) 0.98, 90% interval 0.89 to 1.07.
Homologues: Orthologues: chimpanzee ZNF324B (99% identical), mouse Zfp324 (68% identical), rat Zfp324 (67% identical), Drosophila melanogaster CG6654 (21% identical), Drosophila melanogaster dwg (20% identical), tropical clawed frog znf770 (15% identical), zebrafish 42sp43 (14% identical), Caenorhabditis elegans pat-9 (10% identical). Paralogues in human: ZNF324 (87% identical), ZBTB47 (24% identical), ZNF513 (23% identical), ZNF652 (22% identical), GTF3A (18% identical), ZUP1 (9% identical).
Diseases named in the same sentence as ZNF324B in open-access papers:
ZNF324B is named in the same sentence as 3 diseases in open-access papers, as found by Europe PMC text mining. Sharing a sentence is not in itself a finding about the gene and the disease. The quoted sentences say what the papers report.
head and neck cancer (1 paper, 2021). A primary or metastatic malignant neoplasm affecting the head and neck. "The expression of ZNF324B, together with five other genes, could predict TCGA head and neck cancer patients’ prognosis." (PMID 34638319, 2021).
cancer (1 paper, 2021). A tumor composed of atypical neoplastic, often pleomorphic cells that invade other tissues. "Here, we demonstrate that the overexpression of ZNF250, ZNF324B, and ZNF331 is significantly negatively associated with tumor dedifferentiation status and that higher-grade tumors (with cancer stemness characteristics) express substantially lower levels of those transcription factors." (PMID 34638319, 2021).
ZNF324B also shares sentences with these, for which no sentence is quoted: tumor (1 paper).